CD4 (CD4 molecule)
Diseases named in the same sentence as CD4 in open-access papers (continued):
Sharing a sentence is not in itself a finding about the gene and the disease.
multiple sclerosis (continued). "The rs3194051 polymorphism, a tag SNP of IL7R haplotype 4 in European populations, has been associated with highest CD127 on CD4+ T-cell, higher frequencies of recent thymic emigrants, and lower plasma sCD127 levels in patients with multiple sclerosis." (PMID 26123260, 2015). "Our findings establish that TCF-1 expression in human CD4+ T cells is linked to multiple sclerosis and that treatment with FTY720 increases TCF-1 expression, which regulates IFN-γ and GZMB production." (PMID 26714756, 2015). "In vitro experiments confirmed that anergy induction efficiently prevents responses against disease-associated autoantigens in CD4+ T cells of patients with autoimmune pathologies, including multiple sclerosis, T1D, or RA." (PMID 26441992, 2015). "In the murine EAE model of multiple sclerosis, the exact opposite trend was observed, with Nrp1-deficient CD4+ T cells proliferating more than Nrp1+ cells." (PMID 25343644, 2014). "Relapses in multiple sclerosis (MS) are caused by focal inflammatory lesions, consisting of activated macrophages and CD4+ and CD8+ T-cells, in the central nervous system (CNS)." (PMID 23226199, 2012). "CD4+ T cells capable of cytotoxicity are thought to be involved in the process of multiple sclerosis, whether by causing damage or by helping through the controlled elimination of other pro-inflammatory cells." (PMID 40255388, 2025). "Indeed, Mcam+ endothelial cells promote infiltration of pathogenic CD4+ lymphocytes in a murine model of experimental autoimmune encephalomyelitis and multiple sclerosis lesions." (PMID 37691115, 2023). "CD8+ T cells outnumber CD4+ cells in multiple sclerosis (MS) lesions associated with disease progression, but the pathogenic role and antigenic targets of these clonally expanded effectors are unknown." (PMID 37676734, 2023). "Daclizumab (targeting IL-2Ralpha chain) therapy may relieve the symptoms of multiple sclerosis patients, which is associated with expansion of CD56bright NK cells and a gradual decline in circulating CD4+ T cells." (PMID 35172900, 2022). "In multiple sclerosis, the potential pathogenic characteristics of CD4 + CD28− T cells including cytotoxic and proliferation could be augmented by IL-15." (PMID 36320075, 2022). "A study of isolated CD4+ T and CD8+ T cells from patients with multiple sclerosis revealed an expansion of the PSGL-1+CD4+ T cell population and linked PSGL-1 expression to the ability of CD4+ T cells to transmigrate blood-brain-barrier-derived endothelial cells." (PMID 33708224, 2021). "In addition, CD4+CCR5+CCR2+ T cells are found in cerebrospinal fluid associated with episodes of relapse in multiple sclerosis, and these cells demonstrate an enhanced ability to migrate across a model of the blood-brain barrier." (PMID 29469805, 2018). "We have demonstrated that ex vivo CD4+ T-cell THEMIS expression shows a significant inverse correlation with carriage of the multiple sclerosis risk allele, and that this correlation is also reflected in protein expression; we found an equivalent trend in CD8+ T-cells." (PMID 27438997, 2016). "Indeed, as for CD8 T cells, α4β1 integrin is implicated for CD4 T cell migration, and is a therapeutic target in multiple sclerosis." (PMID 23717511, 2013). "Indeed, targeting α4-integrin with a blocking antibody in patients with multiple sclerosis suppressed CNS accumulation of CD4 T cells and reduced the risk of the rate of clinical relapse." (PMID 23717511, 2013). "Multiple sclerosis patients with eosinophilia from parasitic infestation have markedly reduced episodes of relapses and new MRI lesions in brain associated with increased CD4+CD25+ Treg." (PMID 23935597, 2013). "The chemokine receptors expressed by T helper cells may be important reports allowing the association between multiple sclerosis and CNS infiltrated CD4 cells and monocytes." (PMID 22096627, 2011).
multiple sclerosis (continued). "In addition, our findings are fully in line with our previous study using cohorts of patients with multiple sclerosis, in which we demonstrated a strong association between Vav1 expression, susceptibility to multiple sclerosis and production of inflammatory cytokines by CD4 T cells." (PMID 27438086, 2016). "However, in a mouse model of experimental autoimmune encephalomyelitis (EAE), which depends on CD4+ T cell function and mimics multiple features of the human disease multiple sclerosis, Shcbp1 deficient mice had reduced disease severity and improved survival, and this effect was T cell intrinsic." (PMID 25153088, 2014). "CD4+T cells are being recognized as important immunometabolic modulators in the pathophysiology of neurodegenerative disorders (ND), including multiple sclerosis (MS), Parkinson's disease (PD), and Alzheimer's disease (AD)." (PMID 41742223, 2026). "Using 2 human multiple sclerosis (MS) datasets, we show that POU2AF1, the gene encoding OCA-B, is elevated in CD4+ T cells from patients with MS." (PMID 40299553, 2025). "Given the well-established role of T cells in the pathogenesis of multiple sclerosis (MS), we sought to characterize the phenotype of CD4+ and CD8+ T-cell populations in greater detail." (PMID 40661940, 2025). "T cells play a central role in multiple sclerosis (MS) pathogenesis, with both CD4+ and CD8+ subsets contributing to neuroinflammation and disease progression." (PMID 40661940, 2025). "IL-10+ CD4+ T cells co-expressing IFN-γ or IL-17A have also been described in the affected tissues of animal models of multiple sclerosis and uveitis." (PMID 40433375, 2025). "CD4+ NKT cell numbers are reduced in patients with multiple sclerosis, and they can improve the state of the disease by directing immune responses toward a Th2 response." (PMID 40659713, 2025). "Single-cell mass cytometry profiling revealed a periventricular accumulation of both CD8+ and CD4+ T cells as well as CD56bright natural killer (NK) cells in multiple sclerosis." (PMID 40510352, 2025). "We next ran RCSP on 137 samples collected from CD4+ T cells of multiple sclerosis (MS; GSE137143) as well as Perturb-seq data of 1,989,578 K562 cells, which can be genetically engineered into artificial antigen-presenting cells for expanding T cells." (PMID 40042510, 2025). "For instance, in multiple sclerosis (MS), autoreactive memory CD4+ T cells specific for myelin antigens mediate central nervous system (CNS) inflammation." (PMID 40006751, 2025). "In multiple sclerosis (MS), TEMs, including both CD4+ and CD8+ T cells, are involved in the inflammatory response that leads to the destruction of the myelin sheath in the central nervous system (CNS)." (PMID 40006751, 2025). "ST14 was identified as an immune ligand for MCAM, which was enriched in CD4+ T lymphocytes that cross the BBB in multiple sclerosis lesions." (PMID 41388158, 2025). "EAE is a CD4+ T cell-mediated disease model of multiple sclerosis, and the generation of effector CD4+ T cells is a critical event in the progression of EAE." (PMID 40264755, 2025). "Our findings are supported by CB2R-mediated cytokine reduction from CD4+ T cells treated with lenabasum in a multiple sclerosis model." (PMID 40383862, 2025). "In contrast, antigen-independent reactivation of CD4+ memory TIA cells accelerates disease onset in an autoimmune model of multiple sclerosis." (PMID 38838013, 2024). "In experimental autoimmune encephalomyelitis (EAE, a mouse model for multiple sclerosis), CD4+ and CD8+ T cells accumulate in the choroid plexus and enter the CSF during neuroinflammation." (PMID 38874395, 2024). "CD4+CD25+ regulatory T cells (Tregs) play an important role in maintaining immune homeostasis in multiple sclerosis (MS)." (PMID 38491084, 2024). "While CD8+ T cells predominate in multiple sclerosis (MS), CD4+ T cells are more numerous when perivascularly infiltrated in the brain parenchyma lesions with NMOSD and MOGAD." (PMID 38334017, 2024).
multiple sclerosis (continued). "In our study, we showed that Dleu2-17aa treatment ameliorated EAE, a mouse model of multiple sclerosis, by reducing the numbers of inflammatory/effector CD4+ T cells and increasing the frequency of Treg cells in both the spleen and CNS of EAE mice." (PMID 38291338, 2024). "Heightened plasma and CSF IL-15 has also been described in patients suffering from multiple sclerosis: peripheral inflammation would facilitate the expression of chemokines and adhesion molecules on CD4+ T cells, thus allowing their migration into CNS." (PMID 38704619, 2024). "In patients with multiple sclerosis, heterogeneity of gene expression has been documented in naïve CD4 T cells that suggest bias in gene expression potential can exist prior to antigen encounter." (PMID 38887299, 2024). "Inflammation induced by autoreactive CD4+ T lymphocytes is a major factor in the pathogenesis of multiple sclerosis (MS)." (PMID 37170724, 2023). "The analysis of three distinct multiple sclerosis (MS) datasets—post-mortem white matter lesions, CD4+ T cells, and CD19+ T cells – has unveiled 146 novel potential disease-associated candidate genes." (PMID 37872607, 2023). "Nevertheless, in the multiple sclerosis patients, both CD4+ and CD8+ T-cells correlated significantly with ALC from treatment initiation to week 96 of observation (r = 0.559−0.880; p < 0.001)." (PMID 37377785, 2023). "Demyelination and axonal injury, the histopathology hallmarks of multiple sclerosis, are thought to arise from an immune-mediated attack on myelinated axons and the myelin sheath, involving CD4+ T cells, cytotoxic CD8+ T cells, B cells, and macrophages." (PMID 36604748, 2023). "In the same line, a recent study of multiple sclerosis pathogenesis identified autoreactive CD4+ T cell clones that can respond to self-peptides as well as peptides from EBV and from the bacteria Akkermansis muciniphila." (PMID 36995951, 2023). "The key role played by the adaptive immune system, and, in particular, by CD4+ T helper (Th) lymphocytes, in inflammation-driven neurodegenerative diseases such as multiple sclerosis and Parkinson’s disease was widely investigated." (PMID 37834328, 2023). "Nevertheless, human CD4 T-cells can be induced to express CD103 through various stimuli in vitro and the percentage of CD103+ cells among CD4+ CD25+ T-cells is significantly higher than CD4+CD25− T-cells in patients with multiple sclerosis." (PMID 38283365, 2023). "There is an analogous distribution of CD4+ T cells in healthy human brains obtained from temporal lobe surgery and in brain lesions of multiple sclerosis (MS) patients, with Tregs making up 10-30% of CD4+ T cells." (PMID 37197653, 2023). "In our study, we observed that the impact of exosomes derived from astrocytes with various functional phenotype differently affect the immune response of CD4+ T cells, both from healthy individuals and from patients with multiple sclerosis (MS)." (PMID 37108633, 2023). "The immune response in multiple sclerosis involves the participation of CD4+ T cells that produce cytokines and chemokines." (PMID 36140164, 2022). "CYFIP2 is highly abundant in CD4+ cells from multiple sclerosis patients and is involved in T cell adhesion, and ABLIM3 is a component of adherent junctions with actin‐binding activity." (PMID 35124891, 2022). "Imaging of CD4+ T cells has an increasingly important role reflecting the pivotal role of CD4+ T cells in many inflammatory diseases including RA, inflammatory bowel disease and multiple sclerosis." (PMID 36114433, 2022). "Presentation of self-antigens by dendritic cells is thought to be key to the activation of these effector CD4+ T cells in multiple sclerosis." (PMID 35915507, 2022). "Numerous studies currently focusing on multiple sclerosis highlight the involvement of many major immune cell subsets, such as CD4+ T cells, CD8+ T cells and more recently B cells." (PMID 36292995, 2022).
multiple sclerosis (continued). "Studies in multiple sclerosis characterised CD4+CD25+Foxp3hiHLA-DR+ Treg, which are highly suppressive." (PMID 36426347, 2022). "Experimental allergic encephalomyelitis (EAE), characterized by CD4+ T cells-mediated inflammation and demyelination, is an ideal animal model for human multiple sclerosis (MS)." (PMID 35252186, 2022). "A similar effect with a reduction of inflammation was achieved by the conditional deletion of IGF1R in CD4+ cells in multiple sclerosis." (PMID 36105797, 2022). "Central to multiple sclerosis pathogenesis is the destruction of axonal myelin sheath by autoreactive CD4+ T cells, namely those of the pro-inflammatory Th1 and Th17 subtypes, in several regions of the brain and spinal cord." (PMID 35915507, 2022). "Differentiation of CD4+ T cells into Th17 cells is an important factor in the onset and progression of multiple sclerosis (MS) and Th17/Treg imbalance." (PMID 35266286, 2022). "The direct comparison of gene expression between multiple sclerosis andnon-inflammatory control CSF CD4+ T-cells yielded 140 significantgenes and GO analysis identified 31 enriched terms." (PMID 34761221, 2021). "In intestinal biopsies from patients with multiple sclerosis, Smad7 was found to favor the expansion of intestinal CD4+ T cells toward an inflammatory phenotype and promote the migration of intestinal CD4+ T cells to the CNS." (PMID 34059951, 2021). "Here, we establish a genome-wide map of DNA methylation quantitative trait loci in CD4+ T-cells isolated from multiple sclerosis patients." (PMID 34873174, 2021). "Four genes were identified that were differentiallyexpressed in multiple sclerosis CSF CD4+ T-cells at FDR<5%: oneup-regulated and three down-regulated." (PMID 34761221, 2021). "Interleukin (IL)-16, a CD4+ immune cell specific chemoattractant cytokine, has been shown to be involved in the development of multiple sclerosis, an inflammatory demyelinating disease of the central nervous system (CNS)." (PMID 34071825, 2021). "The sphingosine-1-phosphate receptor regulator fingolimod (FTY720) is an effective immunology modulator that targets CD4 T cells, which has been widely used in multiple sclerosis with a proven safety profile." (PMID 34646783, 2021). "Multiple sclerosis (MS) is an inflammatory disease involving a CD4+ T-cell-driven autoimmune response to central nervous system (CNS) derived antigens." (PMID 34920747, 2021). "We conclude that Trojan Horse delivery of the biologic “LIF” into the brain using LIF-loaded PLGA nanoparticles functionalized with anti-CD4 is a validated therapeutic candidate to treat multiple sclerosis." (PMID 35047909, 2021). "In multiple sclerosis, miR-193a was strongly upregulated in CD4+ lymphocytes in response to CD3/CD28 stimulation, suggesting miRNA-dependent regulatory involvement in immune function." (PMID 33535558, 2021). "Lymphocyte homing mechanisms that permit CNS-specific CD4+ T-cellextravasation contain potential targets for treating CNS inflammatory disorders,such as multiple sclerosis." (PMID 34761221, 2021). "In support of this concept, elegant studies have shown that blood B cells from patients with multiple sclerosis presented self-peptides to brain-homing CD4 T cells." (PMID 33822842, 2021). "Pairedcomparisons between CD4+ T-cells from CSF and blood identified5156 differentially expressed genes in controls and 4263 differentiallyexpressed in multiple sclerosis patients at false discovery rate<5%." (PMID 34761221, 2021). "Their studies provided the direct link between the presence of CD4+GranzB+CTLs and multiple sclerosis (MS) disease severity." (PMID 34641948, 2021). "For instance, in splenic CD4+ T cells from mouse models of multiple sclerosis, CBD treatment (10 mg/kg, i.p.)affected miRNAs in both directions, i.e., it increased the expression of certain ones and decreased the expression of others." (PMID 33668469, 2021).
multiple sclerosis (continued). "Until now, only one work that studied the effect of IL-15 on the migration capacity of the CD4+CD28null T lymphocytes has been published, and in that case, it was made in multiple sclerosis patients." (PMID 34202487, 2021). "This fact makes it possible to extrapolate these results to any situation where the CD4+CD28null T cell subset is expanded, as is the case with multiple sclerosis or RA." (PMID 34202487, 2021). "Previous studies have reported reduction of the Parabacteroides in multiple sclerosis patients where its exerts a protective role by stimulating anti-inflammatory IL-10–expressing human CD4+CD25+ T cells." (PMID 33546364, 2021). "In end-stage renal disease patients, the frequency of CD4+CD57+ T-cells is associated with atherosclerotic changes, and in multiple sclerosis, their frequency is associated with disease severity and poorer prognosis." (PMID 34576140, 2021). "Peripheral blood mononuclear cells derived from multiple sclerosis patients have been used to determine differences in migration of CD4+ T cell subpopulations in vitro using a transwell migration assay." (PMID 34527702, 2021). "Studies in brain tissue of patients with multiple sclerosis have found infiltration of CD4 and CD8 T cells, and both cell types have shown positivity to IL-17." (PMID 34488776, 2021). "Microarray analysis revealed that the change in Smad7 expression following treatment with IVMP, in relapsing–remitting in patients with multiple sclerosis (in vivo), was significantly lower than that in CD4+ T cells from healthy donors (in vitro)." (PMID 34059951, 2021). "Immunotherapy with antigen-processing independent T cell epitopes (apitopes) targeting autoreactive CD4+ T cells has translated to the clinic and been shown to modulate progression of both Graves’ disease and multiple sclerosis." (PMID 33936079, 2021). "These EOMES+CD4+ T cells were found to be increased in the peripheral blood and cerebrospinal fluid from patients with multiple sclerosis." (PMID 32190092, 2020). "Prevotella histicola increases tolerogenic responses (including expansion of CD4+FoxP3+Tregs in the spleens and mesenteric lymph nodes of mice in which experimental autoimmune encephalitis (a model of human multiple sclerosis) is attenuated." (PMID 32574158, 2020). "Little is known about the role of IL-3 in ischemic stroke; however, it is produced by activated CD4+/CD8+ T cells and has been implicated in the development of neuroinflammatory conditions such as multiple sclerosis." (PMID 33376583, 2020). "As a prevalent autoimmune disease of the central nervous system in young adults, multiple sclerosis (MS) is mediated by T cells, particularly CD4+ subsets." (PMID 33354282, 2020). "For example, in a multiple sclerosis mouse model HGF/SF has been shown to modulate both CD4+ and CD8+ T cell effector responses." (PMID 33198383, 2020). "Nineteen miRNAs (including miR18a that belongs to miR 17-92 cluster) were found differentially expressed in naive CD4 T cells multiple sclerosis patients and predicted to target TGFβ." (PMID 32973667, 2020). "The presence of the unique subpopulation of CD4+ T lymphocytes has also been reported in other autoimmune conditions, such as multiple sclerosis, AS or IBD." (PMID 32123296, 2020). "It has been shown that memory B cells of some multiple sclerosis patients induced proliferation of CD4 T cells targeting CNS self-antigens while memory B cells of healthy controls did not support this effect." (PMID 32716916, 2020). "In an animal model for multiple sclerosis, knock-out of Cdcp1 led to improved clinical scores and reduced infiltration of CD4+ T cells producing IFN-γ and IL-17." (PMID 32983115, 2020). "These miRNAs negatively regulated the TGFβ pathway (TGFBR1 and SMAD4 were significantly reduced in patients with multiple sclerosis), resulting in a decreased capacity of naive CD4 T cells to generate regulatory T cells." (PMID 32973667, 2020).